IL11 (interleukin 11)
Diseases named in the same sentence as IL11 in open-access papers (continued):
Sharing a sentence is not in itself a finding about the gene and the disease.
tumor (continued). "Low expression of IL‐11 in tumour cells was associated with significantly higher levels of leukocytes (CD45), T cells (CD3, CD4, CD8), T‐cell activation (CD44, CD25, ICOS, Tim3), dendritic cell activation, antigen presentation (CD11c, CD80, B2M, HLA‐DR) and macrophage (CD68) markers." (PMID 40673604, 2025). "Therefore, high levels of IL‐11 are associated with a complex microenvironment that drives tumour progression and immunosuppression." (PMID 40673604, 2025). "In addition, a significant (p = 0.004) reduction in IL-11, an IL-6 associated cytokine was also was also observed, which we previously observed to be upregulated in a tumor-intrinsic setting." (PMID 38831884, 2024). "In GC, IL-11 is associated with tumor progression, invasion, and poor survival outcomes." (PMID 38542101, 2024). "Moreover, IL-11 secreted from cancer-associated fibroblasts in response to TGF-β activates gp130/STAT3 signalling to promote the survival of metastatic tumour cells." (PMID 38600086, 2024). "The “seed and soil” theory postulates that tumor cells produce several tumor-associated factors, including interleukins (IL-1β, IL-6, IL-8, IL-11, IL-17), macrophage inflammatory protein 1α, TNFα, parathyroid hormone-releasing protein (PTHrP), and prostaglandin E (PGE2)." (PMID 36294305, 2022). "In this narrative review, we discuss the mechanisms by which IL11 may promote NSCLC tumor growth and summarize the evidence regarding the diagnostic and prognostic utility of IL11 specifically in NSCLC." (PMID 35883698, 2022). "During PCa bone metastasis, TGF-β acts on tumor cells to induce the secretion of paracrine signaling molecules to support their survival and growth; and some of them are osteolytic factors (e.g., PTHrP, IL-11, VEGF, and MMPs) that cause osteolytic resorption." (PMID 33731701, 2021). "Elucidation of the mechanisms underlying IL-11 production by fibroblasts in the tumor microenvironment may be crucial for understanding how tumor cells instruct stromal cells." (PMID 33863879, 2021). "Indeed, IL11 expression has been shown to correlate with risk of developing bone metastasis and is higher in both tumour and serum samples from BC patients who presented these distant metastatic lesions." (PMID 34834425, 2021). "Moreover, transcript levels of genes associated with CRC susceptibility loci (e.g., Grem1 and Bmp4) and tumor development and invasion (e.g., Wnt5a, Ereg, Mmp3, Mmp13, Timp1, Saa3, Ptgs2, and Acsl4) were elevated in IL-11+ fibroblasts." (PMID 33863879, 2021). "IL-11 is also associated with endometrial cancer, and is associated with increasing tumor grade." (PMID 32765502, 2020). "However, in human CRC tissues and CRC mouse models, IL-6 is produced mostly from activated myeloid cells in the tumor microenvironment, while IL-11 is produced mostly by cancer-associated fibroblasts (CAFs) and myeloid cells." (PMID 31754344, 2019). "Collectively, these results suggest that the functional loss of miR-124 might result in enhanced IL-11 expression, which promotes the development of osteolytic lesions and eventually favors tumor progression." (PMID 29343249, 2018). "Recently, IL-11 has demonstrated an emergent role in several inflammation-associated tumours." (PMID 29089667, 2017). "Additionally, IL11 and IL11Rα overexpression are associated with tumour progression, growth and differentiation and poor prognosis in colorectal, gastric, hepatocellular and breast cancers." (PMID 28186993, 2017). "From these data, we speculated that IL-11 induction at tumour sites is associated with enhanced expression of arginase-1, VEGF, TGF-β, and IL-10, which may be involved in the suppression of T cell responses in the tumour microenvironment." (PMID 28781374, 2015). "It is also possible that IL11 may be secreted by the cancer associated leukocytes into the uterine lumen in the Grade 3 tumours thereby contributing to the IL11 levels found in the lavage fluid." (PMID 20553623, 2010).
tumor (continued). "We next ascertained that the striking anti‐tumor effect of bazedoxifene treatment also extended to the epithelium of the small intestine, which is also susceptible to the therapeutic benefit conferred by inhibition of the IL11/STAT3 signaling axis at the level of the gp130‐associated JAK1/2 kinases." (PMID 30885958, 2019). "Elevated IL‐11 is generally correlated to a higher tumor grade except for in the setting of bladder cancer." (PMID 40968783, 2026). "More importantly, the knockdown of IL‐11 or IL‐11R in HCC1937 cells resulted in a significant reduction in tumor growth in Nude mice, by 60.7% and 82.1% respectively." (PMID 41178513, 2026). "In an orthotopic tumor model, IL‐11 overexpressing 231‐GFP cells grew more rapidly and formed tumors that were 4.8 times larger in Nude mice." (PMID 41178513, 2026). "In LUAD cells, shGαi1/3 inhibited cell growth, proliferation, and migration as well as blocked the tumor-promoting ability of IL-11." (PMID 42034606, 2026). "FABP7 upregulation promotes IL11 and other immunomodulatory factors, influencing the tumor immune microenvironment (TIME) and correlating with patient prognosis." (PMID 41487426, 2025). "Antibody targeting of the IL‐11 receptor (IL‐11RA) shows significant anti‐tumour effects in a patient‐derived xenograft model highlighting IL‐11 as a compelling therapeutic target." (PMID 40673604, 2025). "The IL‐11/IL‐11RA signalling pathway and tumour proliferation were significantly down‐regulated as assessed by IHC staining of pSTAT3, and cyclin D1 and Ki67, respectively." (PMID 40673604, 2025). "Previous studies have demonstrated that the pharmacological blockade of IL‐11 signalling has anti‐tumour effects." (PMID 40673604, 2025). "IL-11 is a pleiotropic cytokine belonging to the IL-6-related cytokine family that has recently emerged as a tumor-promoting biomarker." (PMID 40426949, 2025). "IL-11 overexpression promotes tumor progression and T cell dysfunction, whereas IL-11 knockdown reverses lactate-induced CD8+ T cell exhaustion, and cholesterol-modified siIL11 restores cytotoxic activity, improving immunotherapy efficacy." (PMID 41194917, 2025). "Our findings revealed a pivotal role for IL‐11 in driving tumourigenesis across various mouse models, highlighting its capacity to modulate tumour immunity towards an immunosuppressive microenvironment." (PMID 40673604, 2025). "In summary, all these data demonstrated that IL‐11 promotes tumour progression across different LUAD mice models." (PMID 40673604, 2025). "In order to identify appropriate strategies to treat such patients, further studies are needed to decipher the mechanism of IL‐11 in tumour cells and the stroma compartment, and of the nature of IL‐11's crosstalk with the TME." (PMID 40673604, 2025). "Of the iCAF signature expressing subsets specific to cancers, IGF1 + CAF and IL11 + CAF were abundant in tumours." (PMID 39757146, 2025). "Co‐injection of cells overexpressing IL‐11 and IL‐11RA increased tumour growth significantly with respect to the control group." (PMID 40673604, 2025). "Subgroup one was enriched with tumour samples expressing high levels of IL‐11 (>75%, n = 16) whereas subgroup two was enriched in tumour samples with low levels of IL‐11 expression (<25%, n = 16)." (PMID 40673604, 2025). "Pro-inflammatory cytokines, such as TNF-α, IL-6, and IL-11, mediate the tumor-promoting function of M2 macrophages in cancer cells by activating the NF-κB/STAT3 pathways." (PMID 40422244, 2025). "Here, we present evidence that IL‐11 plays a major role in exacerbating tumour cell growth mediated through STAT3 and STAT1 activation." (PMID 40673604, 2025). "NRF2 promotes metastasis by regulating epithelial-mesenchymal transition and modulating cytokine production—suppressing pro-inflammatory cytokines (e.g., IL-6, IL-1β) while inducing tumor-promoting ones like IL-11." (PMID 41187427, 2025).
tumor (continued). "Immunohistochemistry staining of tumour sections showed an increase in the levels of pSTAT3 and cyclin D1 in IL‐11‐treated mice." (PMID 40673604, 2025). "In endometrial cancer, elevated IL-31 and IL-33 levels correlate with tumor stage, serving as prognostic biomarkers, while IL-11 blockade reduces tumor growth and metastasis in mouse models." (PMID 41029427, 2025). "Other potentially stiffness regulated genes were IL-33, HS3ST3B1, and IL-11, which were among the most differentially expressed genes between the PDECs grown in the soft matrix compared to the original uncultured stiff tumor." (PMID 40425576, 2025). "Our OIRRA data showed that tumour samples that express high levels of IL‐11 also up‐regulate IL‐6 expression, potentially triggered by TGFB." (PMID 40673604, 2025). "Some recent studies indicated that ATB, activated by TGF-β, promotes tumor progression, micro- and macrovascular metastasis, vascular invasion, and colonization of distant malignant cells by stimulating IL-11 secretion." (PMID 40487253, 2025). "Here, we show that those patients with high IL‐11 cytokine expression levels have down‐regulated the expression of genes involved in the anti‐tumour immune response, whereas genes that participates in immune evasion and tumour progression are overexpressed." (PMID 40673604, 2025). "In the subgroup of patient tumour samples with an elevated accumulation of IL‐11, EMT genes (SNAI1, AXL and TWIST1) and hypoxia factor 1 (HIF1A) were over‐expressed compared with the subtype with a lower accumulation of IL‐11." (PMID 40673604, 2025). "IL‐11 mutein binds to the IL‐11R/gp130 complex and blocks IL‐11/IL‐11RA signal transduction, reducing the tumour growth." (PMID 40673604, 2025). "Cytokines including IL-6, IL-10, IL-11 and IL-24 can suppress immune effector cells, such as T cells, natural killer cells and dendritic cells, impairing the host’s anti-tumour response while facilitating the immune evasion of GBM cells." (PMID 41301734, 2025). "IL‐11's multifaceted impact on both tumour cells and the tumour microenvironment underscores its potential as a therapeutic target in LUAD." (PMID 40673604, 2025). "Tumor cells secrete parathyroid hormone-related protein (PTHrP), interleukin-6 (IL-6), and interleukin-11 (IL-11), which stimulate osteoclast differentiation and activity." (PMID 40426987, 2025). "We further revealed that IL‐11 dysregulates the immunity of the tumour generating an immunosuppressive microenvironment in two murine models of tobacco–induced LUAD." (PMID 40673604, 2025). "Analysis of the TCGA database revealed significantly higher expression of IL6 and IL11 in CRC tumor tissues compared with adjacent normal samples." (PMID 41585878, 2025). "We have also demonstrated that pharmacological inhibition of IL-11 signalling with a small molecule gp130 inhibitor has potent anti-tumor effects in Gp130FF mice and other models of gastrointestinal cancers." (PMID 37957015, 2024). "Studies have illuminated the significant functions of key interleukins, including IL-6, IL-8, IL-1β, and IL-11, in promoting tumor growth, osteoclast development, and metastasis colonization in the skeletal system." (PMID 39125732, 2024). "It is plausible that IL-11 is involved in this gut–kidney axis because it plays a role in communicating between gut dysbiosis and tumor metastasis, as well as gut dysbiosis and liver failure." (PMID 38732588, 2024). "Immunofluorescence images revealed colocalization of the ligand‒receptor pair, providing insight into the spatial dynamics of IL-11 signalling within the tumour microenvironment." (PMID 38429845, 2024). "Col1a1 is overexpressed in GC, and its reduction following IL-11 Mutein treatment further suggests remodeling of the tumor matrix." (PMID 38542101, 2024). "While sporadic expression of IL-11-positive cells were observed in adjacent normal biopsy, IL-11 positivity was more commonly observed in epithelial-like cells in tumor regions." (PMID 39329890, 2024).
tumor (continued). "We found IL6, and IL11 expression was significantly upregulated in patients with primary tumours (n = 1450), as well as in patients with metastatic lesions (n = 99) when compared to expression levels in the normal colon of patients (n = 377)." (PMID 38600086, 2024). "IL-11 is a tumor-promoting cytokine and is involved in the proliferation and migration of precancerous cells through the NF-κΒ signal transduction." (PMID 38702644, 2024). "Lastly, in the NSCLC patients, we observed increased IL-11 gene and protein expression in tumor compared to their adjacent normal tissue biopsies." (PMID 39329890, 2024). "Abrogation of IL-11 signalling markedly impeded tumour progression in vivo, as evidenced by attenuated tumour growth in the IL-11-silenced cohort relative to the controls." (PMID 38429845, 2024). "The results from the flow cytometry experiment were consistent, in that the apoptosis of Jurkat T cells (induced by PC9‐BrM3) was greater when tumor cells were treated with IL11, especially at a higher concentration." (PMID 38696655, 2024). "Animal models that faithfully recapitulate the human tumour microenvironment will be crucial in assessing the therapeutic potential of targeting the IL-11-mediated pathway." (PMID 38429845, 2024). "Given the demonstrated therapeutic benefit of IL-11 signaling inhibition in this model, we also sought to determine if the serum protein signatures that correlated with tumor progression were altered following therapeutic manipulation of tumor burden." (PMID 38542101, 2024). "This study also demonstrated that inhibiting this signalling in IL-11 knock-out mice led to an increase in apoptosis and a decrease in tumour recurrence." (PMID 38248304, 2024). "We found that either modality of IL-11 signaling inhibition significantly reduced overall tumor burden." (PMID 38542101, 2024). "By driving the expression of onco-immune modulatory genes, such as ENO1, MUC1, COL5A1, and IL11, FABP7 enhances tumor-associated immune suppression, particularly by facilitating the infiltration of immunosuppressive cell populations within TIME." (PMID 39596296, 2024). "IL-6 and IL-11 drive tumour cell proliferation, survival, invasiveness and metastasis while suppressing anti-tumour immune responses." (PMID 38600086, 2024). "Studies have highlighted the role of particular ILs, such as IL-1, IL-6, and IL-11, in enhancing osteoclastogenesis, tumor growth, and bone deterioration, underscoring their potential as targets for therapeutic intervention to hinder bone metastases." (PMID 39125732, 2024). "Tumor-promoting cytokines such as IL-11 also induce differentiation of immunosuppression cells through activation of STAT3 signaling pathway." (PMID 38702644, 2024). "In this regard, IL-11 plays an important role in promoting angiogenesis, invasion, and migration of tumor cells, as well as in proinflammation and differentiation of tumor-associated macrophages (TAMs)." (PMID 39199587, 2024). "Specifically, IL-11 has been shown to increase tumour proliferation, migration, invasion, and survival, all important hallmarks of cancer." (PMID 38248304, 2024). "Among risk factor genes, IL11, TRAF1, and DHRS2 were upregulated in the docetaxel-resistant group, indicating consistency with progression of tumour docetaxel resistance and poor prognosis." (PMID 38429845, 2024). "Here, we show that reduced expression of Yap1 in Yap1KD; Gp130FF tumor organoids reduces their capacity to produce IL-11, whereas Yap1 deletion reduces proliferation and survival of neoplastic cells in tumors of Gp130FF; Yap1KO mice." (PMID 37957015, 2024).
tumor (continued). "IL-6, a well-established cytokine induced by IL-1β in intestinal epithelial cells (IECs), has been shown to promote tumor progression in CAC through the activation of the oncogene STAT3 in addition to IL-11." (PMID 38607004, 2024). "On the other hand, elevated STAT3 in the stromal cells of the host confers an immune-suppressed tumor microenvironment, with specific roles identified for IL-6 and IL-11." (PMID 39128004, 2024). "IL11 expression was increased 40-fold in KPP tumors when compared to adjacent non-tumor epithelium, while IL6 expression remained comparable between these two compartments." (PMID 39128004, 2024). "Here, we provide evidence that bazedoxifene inhibits tumour growth via direct interaction with the gp130 receptor to suppress IL-6 and IL-11-mediated STAT3 signalling." (PMID 38600086, 2024). "AOM/DSS model in Il11−/− and Apcmin/+/Il11−/− mice were used to detect tumor growth and CD8+ T infiltration." (PMID 37365574, 2023). "More recently, an immune-modulatory role of IL11 has been reported through its suppressive effect on host CD4+ T cells in the tumor microenvironment." (PMID 37365574, 2023). "IL-11 regulates the “ECM tissue” signal pathway of tumor-promoting genes, and the related inhibitors and blocking pathways have become a new way to inhibit the formation of tumor metastasis." (PMID 37978384, 2023). "There is substantial evidence that IL-11 regulates tumor progression, cellular growth, and differentiation." (PMID 37176567, 2023). "Tumors were significantly suppressed while MHC-I and CXCL9 expression for CD8+ T infiltration were remarkably increased in the tumor tissues of Apcmin/+/Il11−/− mice or Il11−/− mice induced by AOM/DSS." (PMID 37365574, 2023). "Forced secretion of IL11 drastically increased the frequency of tumor formation and reduced the disease latency period." (PMID 36765091, 2023). "IL11 produced by tumour stromal cells suppresses the secretion of pro-inflammatory cytokines (e.g. IFNγ, TNFα, IL6) from CD4+ T-cells and reduces CD+ T cell infiltration, thus promoting immune evasion." (PMID 38054591, 2023). "IL-11 also participates in tumor initiation and progression by regulating epithelial cell turnover and the IL-11/gp130/STAT3 signaling pathway." (PMID 38352248, 2023). "Compared with our findings in Il11−/− mice and focus on IL11 regulation in tumor cell CXCL9 and MHC-I to increase CD8+ T infiltration, Huynh hinted a novel regulation besides IL11Ra for IL11 to exert immune suppression." (PMID 37365574, 2023). "Interleukin-11 (IL-11) belongs to the IL-6 family and has a wide range of functions, including hematopoiesis, bone development, tissue repair, and tumor development." (PMID 37176567, 2023). "Neoplastic plasma cells produce HGF that is cleaved and activated by uPA and plasmin, leading to IL-11 secretion by osteoblasts and tumor cell invasion mediated by osteoclasts, as uPA inhibition also halts MM invasion." (PMID 37445697, 2023). "IL-11 promoted tumor progression by initiating gp130/Stat3 pathway through TLR2, and cancer metastasis was inhibited by blocking the TLR2 signal in mice." (PMID 37153547, 2023). "STAT1 plays a distinct role with STAT3 in IL-11-mediated osteoclastogenesis in the tumor microenvironment." (PMID 36593458, 2023). "Interleukin-11 (IL-11) is a soluble factor in the supernatant of plasma cell tumor-stimulating cells." (PMID 36875689, 2023). "Next, we examined the expression of three ER stress-related cytokines identified from ContactTracing, Ccl2, Cxcl1 and Il11, in 4T1 cells and validated their dependence on tumour-intrinsic STING activation." (PMID 37612508, 2023). "As a member of IL6 family, IL11 is known to promote tumor proliferation and metastasis mainly through activating STAT3 signaling." (PMID 37365574, 2023). "Intraperitoneal injection of IL11 mutein to tumor-bearing mice also showed therapeutic effect to attenuate MC38 growth and weight in vivo." (PMID 37365574, 2023).